MERTK (MER proto-oncogene, tyrosine kinase)
Diseases named in the same sentence as MERTK in open-access papers (continued):
Sharing a sentence is not in itself a finding about the gene and the disease.
tumor (continued). "MERTK blockade by antibodies led to an anti-tumor response characterized by type 1 interferon production, with additive effects after combination with ICB." (PMID 38573347, 2024). "MERTK is a member of the TAM family (TYRO3, AXL, MERTK) of receptor tyrosine kinases and is aberrantly or ectopically expressed in a spectrum of human cancers, where it functions to promote tumor cell survival, metastasis and chemoresistance." (PMID 39199601, 2024). "Foretinib, a multi-kinase inhibitor capable of inhibiting MERTK, has also demonstrated favorable safety profile and promising anti-tumor efficacy across multiple clinical trials." (PMID 39062902, 2024). "We found that INCB081776 inhibited tumor-bound Axl and MerTK kinase activity and downstream signaling pathway activation in mouse oral cancer (MOC) cell lines." (PMID 39457986, 2024). "In this section, we will describe several recent papers regarding immunosuppressive infiltrating MERTK+ cells in several syngeneic tumor models." (PMID 39062902, 2024). "The composition of the tumor microenvironment and the level of MerTK on macrophages in the tumor were evaluted by flow cytometry." (PMID 38443968, 2024). "In this study, we observed a shift in TAM polarization from the pro-tumor M2 phenotype to the anti-tumor M1 phenotype in the secondary tumors of mice treated with XRT+CPI+MerTK ASO." (PMID 38443968, 2024). "Inhibition of MERTK correlated with anti-tumor activity, suggesting MERTK inhibition as a therapeutic mechanism of MRX-2843." (PMID 39199601, 2024). "To identify the specific pathways that were activated or regulated by MerTK, we profiled RNA from SUM102-MerTK clones using the NanoString Tumor Signaling 360 panel (NanoString Technologies, Seattle, WA, USA)." (PMID 38791148, 2024). "This initial excitement dissipated with the generation of a Mertkfl/fl mouse and attempts to probe the cellular basis of MERTK function in anti-tumor immunity." (PMID 38791338, 2024). "The addition of MerTK ASO to the carboplatin+paclitaxel regimen markedly enhanced tumor control in the 344SQR model." (PMID 38443968, 2024). "MER proto-oncogene tyrosine kinase (MERTK) promotes tumor cell survival, metastasis, and resistance to cytotoxic and targeted therapies in a variety of cancers." (PMID 39199601, 2024). "Given the prominent role of MERTK in survival, metastasis, treatment resistance and anti-tumor immunity in a wide range of cancers, MERTK is an attractive target for patients with a spectrum of cancer diagnosis." (PMID 39062902, 2024). "Blockade of MerTK-mediated phagocytosis of dying cancer cells suppresses tumor growth in other cancers." (PMID 38355776, 2024). "Given the lack of any substantive increase in immune pathway activation in the primary tumor induced by adding the MerTK ASO to immunoradiotherapy, we examined these same pathways in the secondary tumor." (PMID 38443968, 2024). "Compared with the control group, tumor volumes and weights were significantly decreased after MerTK‐KO." (PMID 38545840, 2024). "Other antagonistic MERTK antibodies have also been developed that have shown potent anti-tumor effects and enhanced anti-tumor immune response." (PMID 39062902, 2024). "Tumor cell proliferation decreased in all three cell lines with MerTK knockdown (MerTK KD) groups compared with the control and wild‐type groups." (PMID 38545840, 2024). "The discovery that targeting tumor-bound Axl and MerTK significantly influenced the TIME in HNSCC led to our involvement in renewing the UW HNSCC SPORE grant in 2021." (PMID 39457986, 2024). "This dramatic reduction in MerTK expression on the TAMs in the secondary tumor was accompanied by an increase in the M1/M2 ratio, which reached statistical significance for the XRT and XRT+αPD1 treatment groups." (PMID 38443968, 2024).
tumor (continued). "Adding the MerTK ASO to XRT+αPD1 made a much bigger difference to tumor control and animal survival than was the case for XRT+αCTLA4, though both triple combinations achieved similar efficacy in the end." (PMID 38443968, 2024). "Inhibiting the phosphatidylserine receptor Mer tyrosine kinase (MerTK) can reverse the immunosuppressive state induced by efferocytosis, as blocking MerTK-mediated phagocytosis of dying cancer cells has been shown to suppress tumor growth in various cancers." (PMID 39544291, 2024). "To avoid deleterious effects to the eyes, we evaluated an antisense oligonucleotide (ASO) that specifically knocks down MerTK expression on tumor growth in combination with localized radiation (XRT) and αPD1 in a mouse model of anti-PD1-resistant cancer." (PMID 38443968, 2024). "IHC staining revealed a reduced level of proliferation in the MerTK‐KO group compared to that in the control group, indicating an important role for MerTK in tumor growth in vivo." (PMID 38545840, 2024). "In vivo studies also confirmed that MerTK blockade by monoclonal antibodies promoted antitumor immunity, and improved the control of tumors in various tumor models." (PMID 38443968, 2024). "Inhibition of MERTK via RNAi knockdown caused a reduction in NSCLC growth, enhanced chemotherapy sensitivity, and blocked tumor progression in nude mice." (PMID 39062902, 2024). "MERTK represents a multifaceted target in cancer therapy as MERTK inhibition can impact tumor cells directly as well as modulation of the immune system." (PMID 39062902, 2024). "MerTK is a macrophage-specific tyrosine kinase receptor (RTK) that can induce tumor immunological tolerance by inducing macrophage death, polarizing macrophages towards the M2 phenotype, and inhibiting the secretion of inflammatory factors." (PMID 37513975, 2023). "The TAM receptor family of tyrosine kinases, MERTK, Axl and Tyro3, inhibition play a role in tumour development in several cancers and a growing body of evidence points towards a role for TAM receptor signalling in the initiation of EMT." (PMID 38102708, 2023). "In vivo, MerTK antagonism reduces tumor size over time and acts cooperatively with other immunotherapies (e.g. PD-1 blockade)." (PMID 37287967, 2023). "P2X7 was identified as the channel mediating exogenous cGAMP uptake into host tumor-associated macrophages, since P2X7 knockout prevented the ISG signature seen in the tumor microenvironment and stopped tumor regression in response to MerTK blockade." (PMID 37287967, 2023). "The core TAM2-driven genes, including BCAT1, BST2, and MERTK, are involved in regulating tumor progression and TAM2 polarization, which are potential targets for PC therapy." (PMID 37628967, 2023). "Analysis of the tumor microenvironment showed that MERTK blockade reverted the M2 polarization of the macrophages and enhanced the infiltration of CD8+ T cells and their cytotoxic function." (PMID 38203403, 2023). "Among these CARs, CAR M with MerTK intracellular domain exhibits the most phagocytic and anti-tumor activity against tumor cells." (PMID 38017494, 2023). "There is evidence from tumour cell types that differentially glycosylated MERTK isoforms are functionally important in the context of MERTK’s role in oncogenesis." (PMID 37958886, 2023). "All in all, MERTK represents a target in osteolytic bone metastasis to decrease tumor progression and increase bone mass by stimulation of osteoblast differentiation and function and simultaneous inhibition of osteoclast formation." (PMID 38203403, 2023). "During tumor development, MERTK promotes immune evasion and the M2 polarization of macrophages through the regulation of efferocytosis." (PMID 37628967, 2023). "MerTK has been noted in the removal of dying cells, and blockade of MerTK resulted in elevated tumor control." (PMID 36626230, 2023).
tumor (continued). "MerTK inhibition has been evaluated in various tumor models for its cancer cell intrinsic properties, directing the development and testing of MerTK-targeted small molecule inhibitors." (PMID 36960055, 2023). "For verification, we next investigated the phagocytosis of apoptotic tumor cells by MerTK-inhibited M2 phenotype macrophages, which are the most representative macrophage population in tumors." (PMID 36966130, 2023). "Treatment of tumour-bearing mice with the anti-MerTK antibody stimulated T cell activation and synergized with anti-PD-1 or anti-PD-L1 therapy." (PMID 37491279, 2023). "The MerTk extracellular activation domain enables the most significant toxicity against tumor cells among MerTk, TLR2, TLR4, TLR6, and 4-1BB-CD3ζ CAR-M." (PMID 36750830, 2023). "Stimulation with EGF or GAS6 enhanced downstream signaling in parental EGFRMT cells, and EGFR and MERTK shared common signaling pathways that promote tumor cell survival and proliferation, including PI3K/AKT and MAPK/ERK pathways." (PMID 35708914, 2022). "It has been reported that a specific blockade of the macrophage phagocytic receptor MerTK increases the accumulation of apoptotic tumor cells and triggers a type I interferon response." (PMID 36224346, 2022). "Sitravatinib (MGCD516), a spectrum-selective receptor tyrosine kinase inhibitor targeting TAM (TYRO3, AXL, MERTK) and split kinase family receptors, has demonstrated preclinical anti-tumor activity and modulation of tumor microenvironment." (PMID 35767205, 2022). "MerTK expression was decreased in tumor tissue in BRCA and KIRC, predicting better OS in BRCA but worse OS in KIRC." (PMID 36059952, 2022). "MERTK is aberrantly expressed in various cancers and promotes tumor immune evasion and M2 polarization of macrophages through the regulation of efferocytosis." (PMID 36056187, 2022). "The TAM receptors Axl, Tyro3, and MerTk were a family of receptor tyrosine kinases, skew macrophage polarization towards a pro-tumor M2-like phenotype in the tumor microenvironment, and promote apoptotic cell clearance through efferocytosis." (PMID 36059952, 2022). "AXL is a member of the TYRO3, AXL, and MERTK (TAM) family of receptor tyrosine kinases (RTKs) that can be activated by the ligand Gas6, which is closely associated with tumor progression." (PMID 36105100, 2022). "CT053 (free-base form of CT053PTSA) inhibited MET, AXL, VEGFR2, FLT3 and MERTK phosphorylation and suppressed tumor cell angiogenesis by blocking VEGF and HGF, respectively, in vitro." (PMID 36341335, 2022). "To validate, that MERTK in osteoblasts plays a role in tumor–osteoblast interaction, we treated MERTK KO osteoblast cultures again with a conditioned medium of MDA-MB-231, U266, and H460 cancer cells." (PMID 36509738, 2022). "Normally, MerTK releases factors involved in tissue remodeling, immune responses suppression and tumor-promoting." (PMID 36003399, 2022). "In this model, AXL expression is weak in macrophages and high in tumor and DCs, whereas MERTK and TYRO3 expression is marginal in carcinoma cells and restricted to macrophages and DCs." (PMID 35572601, 2022). "Inhibiting phagocytic receptor MerTK to block TAMs‐mediated efferocytosis is another efficient strategy for tumor therapy." (PMID 37323705, 2022). "Both AXL and MERTK play key roles in tumor cell proliferation, migration, invasion, survival and treatment resistance." (PMID 35062934, 2022). "MERTK on TAMs activated and started downstream signaling cascades after indirectly binding to PtdSer on dying tumor cells." (PMID 36497444, 2022). "Inhibitors that target MET, AXL, VEGFR-2, FLT3 and MERTK are becoming research and development hotspots owing to their effect on promoting tumor development and progression." (PMID 36341335, 2022).
tumor (continued). "Similarly, it was speculated that deficient MERTK-dependent phagocytosis by tumor-associated macrophages leads to secondary necrosis of tumor cells and an increased pro-inflammatory microenvironment more conducive to anti-tumor immunity." (PMID 35969037, 2022). "MerTK blockade increases tumor immunogenicity and potentiates antitumor immunity via the transfer of tumor-derived cGAMP into TAMs through the ATP-gated channel P2X7R and subsequent STING activation." (PMID 36224346, 2022). "Collectively, our data demonstrate a role for MERTK as a mediator of oncogenic signaling and driver of residual tumor growth in EGFRMT NSCLCs treated with OSI and provide strong rationale for treatment of EGFRMT NSCLC patients with OSI and MRX-2843 combined." (PMID 35708914, 2022). "CD8+ T cells restrict the metastatic growth of cancer cells from the primary tumor; when MERTK, a tyrosine kinase receptor that inhibits NK cells activation, is inhibited, NK cells have the ability to reject metastatic tumor cells." (PMID 35454769, 2022). "MerTK signaling activation can promote tumor immune tolerance by initiating macrophages efferocytosis and promoting the clearance of immunogenic antigens." (PMID 33463063, 2021). "The results in this study indicated that MERTK in the tumor microenvironment aids malignant tumor progression by suppressing antitumor immunity." (PMID 33562150, 2021). "Several studies have shown that use of inhibitors specific for MERTK have a significant effect on tumor cell growth in cell lines, murine models and patient primary tumor cells." (PMID 34835225, 2021). "Apart from cancer-intrinsic features, MerTK signaling on tumor cells has been shown to also increase expression of PD-L1, potentially limiting cytotoxic T cell antitumoral responses." (PMID 33801886, 2021). "Activation of AXL and/or MERTK leads to signaling cascades that are important for tumor progression." (PMID 34830794, 2021). "Together, Axl and MerTK are essential regulators of physiological vascularization and tumor angiogenesis." (PMID 34771611, 2021). "In recent years, the antitumor efficacy of small molecule inhibitors and MerTK-specific monoclonal antibodies (mAb) was demonstrated in a range of tumor models." (PMID 33801886, 2021). "MERTK is not only upregulated in tumor cells, but also excessively expressed in the surrounding monocytes, macrophages, dendritic cells, and T lymphocytes." (PMID 33562150, 2021). "In our current study, we have shown that tumour PD-L1 activated intra-tumour cell Gas6/MerTK signals which promoted NSCLC cell proliferation in vitro and in vivo." (PMID 33139930, 2021). "A recent publication showed that efferocytosis blockade by inhibiting MerTK-dependent apoptotic tumor cell phagocytosis promotes CD8+ T cell-mediated anti-tumor activity." (PMID 34659260, 2021). "In glioblastoma, higher expression of MerTK is found to be positively related to tumour TNM stage and malignance, leading to poorer survival for patients." (PMID 33139930, 2021). "Since both cancer cells and immune cells express MerTK, it is important to investigate the role of MerTK signaling in the tumor context." (PMID 33801886, 2021). "MerTK inhibition in murine tumor models has also revealed how macrophages and myeloid-derived suppressor cells (MDSCs) are affected in the context of an immune-driven antitumor response." (PMID 33801886, 2021). "Recent studies also indicated high MerTK expression in various tumour tissues, and the activation of MerTK signaling contributed to tumour progression." (PMID 33139930, 2021). "The activation of MERTK in macrophages promotes the phagocytosis of apoptotic tumor cells, which contributes to a macrophage-mediated immunosuppressive tumor environment." (PMID 33562150, 2021). "In these studies, increased inflammatory tumor cell killing was observed when Axl or MerTK signaling was abrogated by small molecule inhibitors, blocking antibodies or gene knockout." (PMID 33801886, 2021).
tumor (continued). "Collectively, all above data indicated that tumour intrinsic PD-L1 promotes cell proliferation via Gas6/MerTK signaling in vitro and in vivo." (PMID 33139930, 2021). "Due to the direct effect MerTK inhibitors have on their respective tumor targets, research into potential off-target effects on other cell types is scarce so far." (PMID 33801886, 2021). "TPIT tumors overexpressed neuronantin, which is silenced by promotor hypermethylation in PitNETs and also MERTK, a receptor tyrosine kinase overexpressed in a variety of neoplasm and a potential therapeutic target." (PMID 34758873, 2021). "Concentration is key in this respect, given that a balance needs to be struck between a direct tumor effect versus any detrimental effect on MerTK+ T cells." (PMID 33801886, 2021). "Recent studies have shown that MERTK inhibition is effective in tumor resolution in in vivo studies, when combining MERTK inhibition with anti-PD-1 blockade in mice." (PMID 34835225, 2021). "INCB081776 treatment also increased total MERTK levels in both tumor models, as well as GAS6 levels in CTG-2041." (PMID 33425754, 2020). "In this review, we will discuss the function of TYRO3, AXL and MERTK on all cells in the tumor micro-environment, with a special focus on T cells." (PMID 31664482, 2020). "Dual targeting of AXL and MERTK led to a more potent inactivation of downstream signaling and reduced tumor growth in vivo compared with targeting either kinase alone." (PMID 33425754, 2020). "Silencing of the MERTK gene increased apoptosis, decreased colony formation, increased chemo-sensitivity, and decreased tumor growth in human non-small cell lung cancer models." (PMID 33425754, 2020). "In cellular assays, INCB081776 effectively blocked autophosphorylation of AXL or MERTK with low nanomolar half maximal inhibitory concentration values in tumor cells and Ba/F3 cells transfected with constitutively active AXL or MERTK." (PMID 33425754, 2020). "MERTK is overexpressed in a variety of tumors, and its overexpression promotes tumor cell proliferation, migration, and invasion." (PMID 32955083, 2020). "During the process of efferocytosis, MERTK and AXL have been implicated as promoters of tumor cell survival in many hematopoietic malignancies, including acute leukemia, chronic leukemia, and multiple myeloma." (PMID 32346605, 2020). "In summary, a total of 119/207 core presenting positive MerTK staining in either stromal mononuclear cells (71/207), cancer cells (34/207), or both (14/207) were observed in the tumor TMA." (PMID 33101282, 2020). "MerTK also plays a prominent role in tumor progression through its expression in the tumor microenvironment." (PMID 33101282, 2020). "Taken together, these results suggest that MerTK+ immunosuppressive myeloid cells are common within the tumor microenvironment and as such represent potential targets for therapies." (PMID 33101282, 2020). "Pre-clinical studies of MERTK inhibitors in murine solid tumor models have shown decreased tumor growth and increased CTL infiltration, while others demonstrated a more profound effect when MerTK inhibition is used in combination with radiation therapy." (PMID 33381449, 2020). "In summary, these data demonstrate that AXL/MERTK inhibition with INCB081776 hinders tumor growth by two distinct mechanisms—reversal of immunosuppression and ablation of intrinsic tumor cell survival signaling." (PMID 33425754, 2020). "Taken together, these results demonstrate the presence of MerTK in immune infiltrate and on tumor cells in multiple solid cancers." (PMID 33101282, 2020). "Based on the clear roles of AXL and MERTK in both immunosuppression and tumor-promoting mechanisms, we set out to develop a potent and selective small molecule dual inhibitor of both AXL and MERTK." (PMID 33425754, 2020). "We place particular focus on TAM receptors and the recently unraveled role of MERTK in activated T cells and potential consequences for anti-tumor immunity." (PMID 31664482, 2020).